TM4SF5 (transmembrane 4 L six family member 5)
Diseases named in the same sentence as TM4SF5 in open-access papers (continued):
Sharing a sentence is not in itself a finding about the gene and the disease.
Obesity (1 paper, 2023). Accumulation of substantial excess body fat. "Under high-fat, carbohydrate, or fructose diets, TM4SF5-overexpressing mice show obesity and NASH-like phenotypes compared to TM4SF5-knockout mice." (PMID 37670786, 2023). "A similar increase in TM4SF5 and apelin levels during obesity or NAFLD development was also found in a public dataset of GSE48325." (PMID 37670786, 2023). "Indeed, suppression of the TM4SF5 downstream effector CCL20 leads to the blockade of HFD-mediated NASH phenotypes, and Tm4sf5−/− KO mice show protection from diet-induced obesity." (PMID 37670786, 2023).
prostate carcinoma (1 paper, 2022). A carcinoma that arises from epithelial cells of the prostate gland. "In addition, we transiently transfected PC3 human prostate cancer cells, which normally exhibit low endogenous TM4SF5 expression, with mouse TM4SF5 expression vector." (PMID 35211652, 2022).
steatosis (1 paper, 2022). Increased lipid within the cytoplasm of cells. "The intracellular movement of GLUT8 and its protein–protein interactions therefore depend on TM4SF5 expression in hepatocytes and are clearly important for fructose uptake/metabolism for excessive fructose-mediated steatosis." (PMID 35123128, 2022). "We next assessed insulin significance during possible TM4SF5-dependent steatosis via NCFD." (PMID 35123128, 2022). "However, whether TM4SF5 is involved in non-alcoholic steatosis via abnormal diets such as excessive fructose intake remains unknown." (PMID 35123128, 2022). "Using liver tissues and blood samples from the mice or hepatocytes, the roles of TM4SF5 in fructose-mediated de novo lipogenesis (DNL) and steatosis via a crosstalk with glucose transporter 8 (GLUT8) were assessed." (PMID 35123128, 2022). "Taken together, our findings have revealed that excessive fructose intake-mediated steatosis under HSuD, NCFD, and/or HFFD conditions involved insulin intolerance, increased TAG, and decreased HDL accumulation in the liver, depending on TM4SF5 expression." (PMID 35123128, 2022). "Overall, hepatic TM4SF5 modulated GLUT8 localization and activity through transient binding, leading to steatosis-related fructose uptake and lipogenesis." (PMID 35123128, 2022). "Tm4sf5 suppression or knockout in both in vitro and in vivo models reduced fructose uptake, DNL, and steatosis." (PMID 35123128, 2022). "Because the findings regarding how 10 weeks of HFD conditioning might affect TM4SF5-dependent mouse steatosis were not easily interpreted, we adopted a short-term approach to assess the effects of excessive fructose intake with NCD- or HFD-pretreatment for one week." (PMID 35123128, 2022).
tumor (26 papers, 2006 to 2026). "TM4SF5 mRNA levels in tumor samples of TCGA–LIHC dataset were positively correlated with hepatic ALB levels." (PMID 40186033, 2025). "Regarding this correlation, human patients with HCC showed higher TM4SF5 expression in tumor regions and metastatically invasive tumor cells (arrows) than in nontumor regions." (PMID 40186033, 2025). "This innovative approach leverages the advantages of exosome-based delivery systems, such as biocompatibility and the ability to cross biological barriers, while exploiting the specific targeting of TM4SF5-expressing tumor cells." (PMID 39273182, 2024). "In the in vivo assessment, administration of TM4SF5-targeting Ex[miR-143], referred to as tEx[miR-143] herein, resulted in the smallest tumor size, the lowest tumor growth rate, and the lightest excised tumors compared to other treatments (p < 0.05)." (PMID 39273182, 2024). "Our findings suggest that TM4SF5-targeting Ex[miR-143] have higher targetability and exhibit promising anti-tumor effects, as evidenced by significant reductions in tumor size, growth rate, and weight." (PMID 39273182, 2024). "The overexpression of TM4SF5 in tumor cells makes it an attractive target for cancer therapeutics, as it can serve as a molecular marker for the selective delivery of treatment to cancer cells while minimizing off-target effects on healthy cells." (PMID 39273182, 2024). "The overexpression of TM4SF5, a protein, is a crucial factor in encouraging the proliferation of tumor cells and is consistently found in hepatocarcinoma patients, contributing to hightened expression of TM4SF5 connected to VEGF level and angiogenesis." (PMID 38611849, 2024). "Among them, TM4SF1, TM4SF4, and TM4SF5 are grouped under the transmembrane 4 L6 domain family, and they have been studied for their expression and roles in various tumor biological activities." (PMID 36678607, 2023). "Tumor tissue from HCC patients had higher TM4SF5 and Smad2/3 phosphorylation levels, implying a possible link between TGFβ1 signaling and TM4SF5 expression in liver carcinogenesis." (PMID 36678607, 2023). "Primarily, TM4SF5-mediated RhoA inactivation promoted EMT, leading to tumor cell migration, invasion, and proliferation due to the loss of contact inhibition." (PMID 36678607, 2023). "Conversely, TM4SF5 affects the internalization of CD63 (a tumor suppressor) from the PM to lysosomes." (PMID 35123128, 2022). "We observed that Ab27 and Ab27-hz9 bound to cell-surface TM4SF5 and were internalized in tumor cells." (PMID 35211652, 2022). "Both antibodies were predominantly localized to the endogenous TM4SF5-expressing tumor, whereas control IgG was mainly detected in the liver." (PMID 35211652, 2022). "Intratumoral injection of Ab27 efficiently decreased ectopic TM4SF5-expressing tumor growth in vivo." (PMID 35211652, 2022). "TM4SF5 is involved in hepatic tumorigenesis and tumor progression, and in fibrotic phenotypes in CCl4-administered mice." (PMID 35123128, 2022). "To validate the tumor-targeting ability of anti-TM4SF5 antibodies, we evaluated the distributions of Ab27 and Ab27-hz9 after injection into the SNU-449Tp xenograft model." (PMID 35211652, 2022). "The anti-TM4SF5 compound TSAHC also inhibits TM4SF5-mediated tumor growth in a manner that is distinct from the antitumor effect of sorafenib." (PMID 35211652, 2022). "Further, administration of CPPs containing the TM4SF5 C-terminal sequence into mice injected with TM4SF5-expressing cells through the tail vein blocked TM4SF5-mediated tumor formation in the lung." (PMID 34335982, 2021). "Meanwhile, TM4SF5 expression-mediated c-Src activity in hepatocytes leads to angiogenesis 67, invasive ECM degradation 25, and immune escape 68, suggesting that TM4SF5-mediated c-Src activation can play multiple roles during TM4SF5-mediated tumor progression." (PMID 34335982, 2021).
tumor (continued). "Cell penetration of TM4SF5 C-terminal peptides blocked the interaction of TM4SF5 with c-Src and prevented c-Src-dependent tumor initiation and progression in vivo." (PMID 34335982, 2021). "TM4SF5 activates integrin-mediated signaling pathways that are pivotal for cell migration/invasion and tumor cell metastasis." (PMID 27816969, 2016). "Xenograft experiments using patient-derived tumor cells have to be performed to evaluate the efficacy of the humanized TM4SF5 antibody for future clinical applications." (PMID 27816969, 2016). "The anti-TM4SF5 monoclonal antibody was specifically localized in the tumor tissues and significantly suppressed tumor growth without prominent side effects." (PMID 25268742, 2014). "When we cut out the tumor mass and analyzed microsections of the frozen tissue, we found that many of the tumor cells were stained with the DyLight 755-labeled anti-TM4SF5 antibody." (PMID 25268742, 2014). "We conclude that a complex of hTM4SF5R2-3 peptide and Lipoplex(O) was effective in eliciting a protective immune response via the generation of specific antibodies that bind to TM4SF5 protein and inhibit tumor growth in vivo." (PMID 22427965, 2012). "We next examined whether treatment with ST-2-001 could abrogate TM4SF5-mediated tumor development in DEN-treated TG mice." (PMID 39828766, 2025). "Furthermore, targeting TM4SF5 has the potential to disrupt critical signaling pathways involved in tumor growth and metastasis, leading to improved therapeutic outcomes." (PMID 39273182, 2024). "Furthermore, TM4SF5 is also expressed in various other tumor types, such as liver (90%), gastric (75%), and pancreatic (70%) cancers, indicating its potential relevance across a wide range of cancers." (PMID 39273182, 2024). "In addition to mediating EMT, TM4SF5 also induced self-renewal and other properties of circulating tumor cells via the interaction with CD44." (PMID 36678607, 2023). "One report recently showed that TM4SF5 expression in HCC tissues was negatively related to tumor malignancy when the tissues were immunostained using a commercial antibody, which was not specific for endogenous or exogenic human TM4SF5 during tissue and cell immunostaining in our hands." (PMID 35955521, 2022). "Both Ab27 and Ab27-hz9 efficiently targeted tumor cells expressing TM4SF5 in vivo." (PMID 35211652, 2022). "Therefore, it can be likely that TM4SF5 transcriptionally regulated gene expression and was involved in tumor progression." (PMID 34921636, 2021). "The expression TM4SF5 could cause internalization of CD63, which resulted in the decrease of CD63 level at the membrane surface and disrupted its tumor-suppressing action." (PMID 33015133, 2020). "TM4SF5 interacted with CD151, and caused the internalization of CD63 from the cell surface into late lysosomal membranes, presumably leading to terminating the tumor-suppressive functions of CD63." (PMID 25033048, 2014). "However, CD63 was excluded from the membrane surface, where it plays a tumor-suppressive role, by the expression of TM4SF5 and/or CD151." (PMID 25033048, 2014). "Therefore, we postulated that TM4SF5-specific monoclonal antibody can serve as a therapeutic antibody to treat these cancers and we recently proved that injection of anti-TM4SF5 antibody can suppress the growth of HCC tumor in a mouse model." (PMID 25268742, 2014). "Here, we analyzed whether the monoclonal antibody produced by immunization with a complex of hTM4SF5R2-3 peptide and Lipoplex(O) can detect TM4SF5 in tumor tissues derived from a HCC mouse model." (PMID 22427965, 2012). "The genes SALL4 and TM4SF5 were expressed to a higher extent in the tumours from deceased patients in our material and have been reported to be up-regulated in other cancers, and may thereby represent putative oncogenes." (PMID 18778486, 2008).
tumor (continued). "Therefore, hepatocyte TM4SF5 might lead to intrahepatic micro-metastasis, expanded tumor size or multifocality via enhanced macropinocytosis resulting from ALB uptake and energetic increases." (PMID 40186033, 2025). "Furthermore, liver tissue from patients with HCC showed increased TM4SF5 expression linked to increased cytosolic staining of NCOA3 in tumor lesions but not in nontumor regions." (PMID 40186033, 2025). "Furthermore, TM4SF5-mediated luciferase signal might be positively correlated with enhanced macropinocytosis, indicating that TM4SF5 plays a role in intrahepatic metastasis, resulting in expanded tumor size or multifocality." (PMID 40186033, 2025). "To examine whether TM4SF5-mediated tumor formation in immune-competent mice might be also targeted by the TSI, we liver-orthotopically injected SNU449Cp or SNU449T7 cells into WT C57BL/6 female mice (n = 4) 1 week before starting 2-week treatment with vehicle DMSO or ST-5-002." (PMID 39828766, 2025). "Targeted therapy of TM4SF5 or TM4SF5/CD44 interaction may effectively inhibit tumor progression." (PMID 35936713, 2022). "Furthermore, we examined whether c-Src activity was important for the TM4SF5-mediated tumor growth by animal xenograft studies." (PMID 28129652, 2017). "Further, we found slightly more TM4SF5 and SLAMF7 in the LAMP1 immunoprecipitates prepared from tumor tissues of TM4SF5-positive patients, compared with those from non-tumor tissues (lanes 3 to 6)." (PMID 39828766, 2025). "Thus, TM4SF5-promoted ALB uptake and catabolism were linked to ATP-linked respiration, supporting efficient cellular migration, which presumably allowed intrahepatic metastasis or achievement of multifocality during tumor nodule expansion or formation and cancer progression in the liver." (PMID 40186033, 2025). "Thus, our observations may support that TM4SF5-expressing HCC cells can utilize extracellular ALB via macropinocytosis for ATP-linked respiration and cell migration, possibly leading to intrahepatic metastasis involving tumor nodule expansion or multifocality." (PMID 40186033, 2025). "In this study, a novel therapeutic strategy was devised to target TM4SF5-expressing cancer cells and suppress MACC-1 function using microRNA-encapsulated Ex, demonstrating promising anti-tumor effects both in vitro and in vivo." (PMID 39273182, 2024). "Intriguingly, Park, Kim found that TM4SF5-transfected PANC02 cells markedly increased cell proliferation and motility, as well as the growth of tumor mass in mice." (PMID 36678607, 2023). "Similar to CPPs containing the TM4SF5 C-terminal sequence, pharmacological inhibition of c-Src activity with PP2 suppressed TM4SF5-dependent tumor formation." (PMID 34335982, 2021). "TM4SF5 promoted self-renewal and circulating tumor cell (CTC) properties, and mediated metastasis through the TM4SF5/CD44/c-Src/STAT3/Twist1/Bmi1 pathway." (PMID 33015133, 2020). "Recently, involvement of TM4SF5 and CD44 in the increase of circulating tumor cells has been suggested in HCC." (PMID 27816969, 2016). "When the tumor size reached 5 mm in diameter, we injected the animals twice a week in the intraperitoneal cavity with PBS, normal mouse IgG, or anti-TM4SF5 monoclonal antibody." (PMID 25268742, 2014). "The expression of TM4SF5 in HCC tumor tissue was confirmed by immunohistochemistry; specifically, the tumor cells were intensively immunostained by anti-hTM4SF5R2-3 peptide monoclonal antibody in the cell membrane and cytosol." (PMID 22427965, 2012). "Here, we investigated how hepatocyte TM4SF5 could modulate extracellular ALB uptake, leading to sufficient ATP synthesis for tumor progression." (PMID 40186033, 2025). "HCC tumor tissues that were positive or negative for TM4SF5 (i.e., increased or decreased TM4SF5 levels, respectively, in tumor tissues compared with non-tumor tissues), showed an inverse pattern in their expression." (PMID 39828766, 2025).
tumor (continued). "In this study, we hypothesize that TM4SF5-targeting Ex (miR-143) can effectively deliver MACC1-suppressing miRNA to CRC cells, resulting in enhanced anti-tumor effects." (PMID 39273182, 2024). "TM4SF4 and TM4SF5 in the L6 family are also involved in tumor regulation, but their exact mechanism is not yet known." (PMID 36209368, 2022). "Indeed, here TM4SF5 knock-out and inhibition (by TSAHC) led to less significant tumor formations in xenografts." (PMID 34921636, 2021). "Moreover, immunostaining of liver tissues from HCC patients showed substantially elevated levels of TM4SF5, laminins, collagen I, and pY705STAT3 in peritumoral (presumably with NASH and fibrosis phenotypes) and tumor regions compared with normal regions." (PMID 34921636, 2021). "Transmembrane 4 L six family member 5 (TM4SF5) is involved in tumorigenesis and tumor progression." (PMID 34335982, 2021). "TM4SF5 regulates diverse cellular functions and behaviors, including actin organization, focal adhesion turnover, cell proliferation, EMT, migration, invasion, drug resistance, and circulating tumor cell and tumor initiating cell properties." (PMID 28458469, 2017). "Although in vivo tumor lesions would be surrounded by complicated soluble factors, ECM, and neighboring cells, TM4SF5-expressing cells may have a greater potential to survive and metastasize even in the presence of fewer complicated environmental cues." (PMID 29137358, 2017). "Similar to TM4SF1, TM4SF5 expression resulted in the internalization of CD63 from the cell surface to the lysosomes, thus decreasing CD63 level on the membrane surface and reducing its tumor suppressive actions." (PMID 25033048, 2014). "This action may decrease the tumor-suppressive functions by CD63, during TM4SF5-mediated liver malignancies." (PMID 25033048, 2014). "Although TM4SF5, CD151, and CD63 can localize to the membrane surface and within the endosome system, their localizations could play critical roles in tumor progression and fibrotic phenotype development in the livers." (PMID 25033048, 2014). "TM4SF5 is also important in HCC formation by inducing morphological elongation, epithelial-mesenchymal transition, abnormal cell growth in multilayers in vitro, and tumor formation in vivo." (PMID 21592346, 2011). "Although a lower extracellular ALB level is a well-known negative prognostic index of HCC, this study can suggest alternatively that a high [ALB]serum (compared with those near lesions) might exaggerate liver malignancy via TM4SF5-dependent ALB uptake and bioenergetics, leading to tumor expansion." (PMID 40186033, 2025). "However, TM4SF5 mRNA expression was nortably increased in tumor samples from patients with HCC compared with in nontumor samples, unlike ALB mRNA levels." (PMID 40186033, 2025). "Among the five genes, analyses of the TCGA + GTXe44 datasets and GSE14520 patients with HCC showed that NCOA3 could be functionally related to TM4SF5 and positively higher in tumor tissues, unlike ALB levels." (PMID 40186033, 2025). "Given that hepatocyte TM4SF5 expression is specifically linked to SLAMF7 downregulation, we further explored whether TM4SF5 expression in NK cells might also lead to NK cell inactivation for tumor development, and how TSI treatment might recover the TM4SF5-mediated SLAMF7 downregulation." (PMID 39828766, 2025). "Furthermore, the tumor lesions from DEN-treated TG mice showed weaker Slamf7 and Nkg2d immunostaining and stronger Tigit and nuclear Ki67 staining compared with non-tumor areas, although TM4SF5 staining was comparable between tumor and non-tumor regions." (PMID 39828766, 2025). "However, the liver tissues of a patient with insignificantly changed TM4SF5 expression (i.e., TM4SF5-independent) showed less SLAMF7 in the LAMP1 immunoprecipitates from tumor tissue compared with that from non-tumor tissue (lanes 1 to 2)." (PMID 39828766, 2025).
tumor (continued). "TM4SF5 influences the epithelial-mesenchymal transition (EMT), aberrant multilayer cellular growth, drug resistance, enhanced migration and invasion, circulation through the bloodstream, tumor-initiation property, metastasis, and muscle development in zebrafish." (PMID 28458469, 2017). "Compared with the control CPP, which did not block tumor formation driven by SNU449Tp cell injection, CPP containing the TM4SF5 C-terminal sequence inhibited tumor formation in a dose-dependent manner without any body weight loss." (PMID 34335982, 2021). "In addition to these binding partners, TM4SF5 binds the tumorigenic tetraspanin CD151, but not tumor-suppressive tetraspanin CD63." (PMID 28458469, 2017).